CDK1 (cyclin dependent kinase 1)
Diseases named in the same sentence as CDK1 in open-access papers (continued):
Sharing a sentence is not in itself a finding about the gene and the disease.
adrenocortical carcinoma (12 papers, 2016 to 2025). "By analyzing the adrenocortical carcinoma dataset in the cancer genome atlas (TCGA), a study found that the increased expression of cyclin-dependent kinase-1 (CDK1) is significantly associated with the adverse clinical outcomes of adrenocortical carcinoma." (PMID 38169587, 2024). "The onset and progression of adrenal cortical carcinoma (ACC) has been linked to CDK1 dysfunction." (PMID 38877579, 2024). "The therapeutic effect of a combination of CDK1 inhibitor CurE and mitotane in adrenocortical carcinoma cells achieves superior therapeutic outcomes through PANoptosis activation compared to monotherapies." (PMID 40721869, 2025). "CDK1 regulated the PANoptosis of adrenocortical carcinoma cells through binding with the PANoptosome in a ZBP1−dependent way." (PMID 39840043, 2024). "ZWINT and CDK1, which correct erroneous centromere-microtubule attachment and regulate the mitotic spindle checkpoint, are mainly involved in cell cycle control in adrenocortical carcinoma." (PMID 34671679, 2021). "The proposed mechanism of action is based on the fact that miR-7 acts on the proto-oncogene RAF-1 and mTOR, and miR-7 therapy inhibits cyclin-dependent kinase 1 (CDK1), which was increased in samples from patients with adrenocortical carcinoma, inversely correlated with miR-7 expression." (PMID 36012357, 2022). "Interestingly, microRNA-7 is downregulated in adrenocortical carcinoma and transfected to the cells and leads to the inhibition of CDK1 gene." (PMID 26912061, 2016). "Meanwhile, the knockdown of CDK1 significantly reduced the ability of invasion and migration via the regulation of EMT proteins in adrenocortical carcinoma cells and head and neck squamous cell carcinomas (HNSCCs) cells." (PMID 37569750, 2023). "Moreover, the CDK1 inhibitor CurE induces ZBP1-dependent PANoptosis and suppresses the proliferation of adrenocortical carcinoma cells, and adenosine deaminase acting on RNA 1 (ADAR1) depletion exerts similar effects under the treatment of NEIs plus IFN-γ in colorectal cancer and melanoma models." (PMID 40721869, 2025).
esophageal cancer (12 papers, 2019 to 2025). A primary or metastatic malignant neoplasm involving the esophagus. "The cell cycle assays demonstrated that COR has the ability to alter the expression of cyclin-dependent kinase 1 (CDK1) and cyclin B1, leading to a blockade of the G2/M phase of the cell cycle in esophageal cancer cells." (PMID 39194034, 2024). "For example, a research team previously confirmed the overexpression of CDK1 in 59 cases of esophageal cancer using real‐time polymerase chain reaction and Western blot." (PMID 34586751, 2021). "In terms of the expression patterns of CDK1 in esophageal cancer, the importance of CDK1 has been demonstrated in some studies." (PMID 34586751, 2021). "The PPI results of the first five KEGG pathway proteins showed that UBE2C mainly influenced the biological function of esophageal cancer by synergistic effects with CDK1, PTTG1, and SKP2 (all three are involved in the cell cycle pathway)." (PMID 34488675, 2021). "Pathway anaylsis showed that UBE2C mainly influenced the biological function of esophageal cancer by synergistic effects with CDK1, PTTG1 and SKP2." (PMID 34488675, 2021). "CDK1/2 overexpression has been reported in CRC and esophageal cancers, CDK4 overexpression has been described in most types of GI tumors and CDK6 overexpression has been observed in CRC and esophageal cancers." (PMID 34503239, 2021). "Previous studies have reported miR-495-3p could target CDK1, cadherin 2, and HMGB1 to display its functional role in various cancers, and BUB1 was demonstrated as the direct target of miR-495-3p in esophageal carcinoma." (PMID 40420658, 2025).
multiple myeloma (12 papers, 2008 to 2025). "Accordingly, a CDK1 inhibitor induces cell death in Burkitt lymphoma and multiple myeloma cell lines depending on MYC levels, and CDK1 inhibition in Eμ-Myc mice results in extended survival." (PMID 30909496, 2019). "Dinaciclib, identified as a candidate drug in the 4,560-drug screen, was also investigated because the Cdk (Cdk1, 2, 5, 9, and 12) inhibitor dinaciclib was reported as an encouraging single agent in multiple myeloma, and the Cdk2/9 inhibitor showed efficacy in CCC organoids." (PMID 40459063, 2025). "Cyclin-dependent kinase 1, an important cell cycle regulator, may be deregulated in multiple myeloma." (PMID 29100463, 2017). "The CDK1/4/9 inhibitor P276-00 showed promising in vitro and in vivo results in AML, myeloma, and mantle cell lymphoma but only achieved SD in two out of 13 R/R mantle cell lymphoma patients in a phase II clinical trial." (PMID 34065376, 2021). "Besides the CDKs targeted by dinaciclib (CDK1, 2, 5, 9), AT7519M also inhibits CDK4, still inducing apoptosis in vitro and in vivo and reducing proliferation in myeloma and CLL." (PMID 34065376, 2021).
thyroid cancer (12 papers, 2013 to 2026). "We subsequently confirmed that CDK1 itself exerted a significant regulatory function in thyroid cancer by loss- and gain-of-function experiments." (PMID 35517403, 2022). "Among them, CDK1 was associated with cell cycle pathways and was involved in proliferation of thyroid cancer cells induced by high iodine." (PMID 33796458, 2021). "The transcriptome analysis showed that there were 295 differentially expressed genes (DEGs) in BCPAP and 8305C cells induced by high iodine, among which CDK1 expression associated with the proliferation of thyroid cancer cells induced by high iodine." (PMID 33796458, 2021). "In addition, overexpression of CDK1 inhibited the apoptosis of thyroid cancer cells, and CDK1 knockdown caused apoptosis promotion of cancer cells (CDK1 overexpression P < 0.001, CDK1 knockdown P < 0.01)." (PMID 35517403, 2022). "A reduction of CDK1 expression may cause a failure in G2 to mitosis transition and arrest in mitotic progression in thyroid cancer cell lines." (PMID 28476040, 2017). "As expected, MTT assay showed that CDK1 overexpression promoted the proliferation of thyroid cancer cells, and vice versa (CDK1 overexpression P < 0.01, CDK1 knockdown P < 0.001)." (PMID 35517403, 2022). "In their work, the ability of CDK1 knockdown arrested cell cycle in G2/M phase in agreement with its role in cell cycle regulation, and the inhibitory function of CDK1 silence on thyroid cancer cell proliferation was also observed in our study." (PMID 35517403, 2022). "Background detection of endogenous CDK1 expression in thyroid cancer cell line also showed that CDK1 had higher expression in B-CPAP and TPC-1 cells compared with another thyroid cancer cell line CAL-62." (PMID 35517403, 2022). "Further studies uncovered that high iodine exerted its roles by activating AKT/Wee1/CDK1 axis and accelerating cell cycle progression in thyroid cancer." (PMID 33796458, 2021). "Overexpression of CDK1 have been found in various type of human cancers, including thyroid cancer, ovarian cancer, colorectal cancer, etc, thus it plays a pivotal role in driving oncogenesis." (PMID 33796458, 2021). "Taken together, these findings suggested that high iodine induced the proliferation of thyroid cancer cells through AKT-mediated Wee1/CDK1 axis, which provided new insights into the regulation of proliferation of thyroid cancer cells by iodine." (PMID 33796458, 2021). "Our data showed that SFN-treated thyroid cancer cells were arrested in G2/M phase, which was accompanied by a decline in the levels of Cdk1, Cdk2, Cyclin B1 and Cdc25C and an increase in the levels of Chk1 and p21." (PMID 26312762, 2015). "Excess iodine may increase the expression of cell cycle–related proteins, such as Wee1 and cyclin-dependent kinase 1 in thyroid cancer cells promoting proliferation." (PMID 41228194, 2025). "In view of the enrichment of DEGs in cyclins and cell cycle regulatory signaling pathways, we speculated that CDCA8 may promote the development of thyroid cancer by upregulating CDK1." (PMID 35517403, 2022). "Further, results of preliminary mechanistic exploration showed that CDK1 may be a potential downstream molecule of CDCA8 in regulating thyroid cancer progression." (PMID 35517403, 2022). "Moreover, CDK1 was identified as a potential target of CDCA8 for exerting its effects on thyroid cancer." (PMID 35517403, 2022). "Moreover, the subsequent mechanism research showed that CDCA8 regulated the expression of CDK1 thus influencing the development of thyroid cancer." (PMID 35517403, 2022). "Importantly, the inhibition of AKT phosphorylation revered the expression of CDK1 induced by high iodine and arrested the cell cycle in the G1 phase, decreasing the proliferation of thyroid cancer cells induced by high iodine." (PMID 33796458, 2021). "Ganetespib significantly represses CDK1 expression that may lead to G2 block and mitotic arrest in thyroid cancer cells." (PMID 28476040, 2017).
thyroid cancer (continued). "LIFR-AS1 was also found to be significantly upregulated in thyroid cancer tissues and cell lines, and its silencing reduced the viability and inhibited the proliferation of human thyroid cancer cells by inducing G2/M cell cycle arrest, possibly through the suppression of cyclin B1 and CDK1." (PMID 35071590, 2022). "Therefore, it was supposed in this study that CDCA8/CDK1 signaling may have substantial contribution in the development and progression of thyroid cancer." (PMID 35517403, 2022). "Additionally, CDK1 has also been found to be vital mediator in the progress of thyroid cancer." (PMID 35517403, 2022). "Additionally, CDK1 was further identified as a potential target of CDCA8 in thyroid cancer." (PMID 35517403, 2022). "However, it is unclear whether CDK1 expression regulated by AKT is involved in the proliferation of thyroid cancer cells induced by iodine via regulating cell cycle progression." (PMID 33796458, 2021). "Therefore, we inferred that AKT/Wee1/CDK1 axis might be activated under exposure to high iodine, thereby promoting the proliferation of developed thyroid cancer cells." (PMID 33796458, 2021). "In order to explore the mechanism of CDCA8 regulating thyroid cancer, we constructed the CDCA8 knockdown and CDK1 overexpression TPC-1 cells, and compared with the results of only CDK1 overexpression cell model." (PMID 35517403, 2022). "More importantly, all the regulatory effects induced by CDK1 overexpression could be alleviated or even reversed by CDCA8 knockdown, indicating its potential as the target of CDCA8 during regulating thyroid cancer." (PMID 35517403, 2022). "This study was designed to explore whether AKT-mediated Wee1/CDK1 axis is involved in the proliferation of PTC and ATC cells induced by high iodine, with a new insights that iodine plays the role on cell proliferation in thyroid cancer." (PMID 33796458, 2021). "The correlations between ganetespib sensitivity and decreases in CDK1 levels, or decreases in phosphorylated or total levels of ERK1/2, AKT, 4E-BP1, S6 ribosomal protein and RET in eight thyroid cancer cell lines were not specifically evaluated in this study." (PMID 28476040, 2017).
renal carcinoma (11 papers, 2018 to 2024). A carcinoma arising from the epithelium of the renal parenchyma or the renal pelvis. "Overexpression of CDC20 and CDK1 has been reported in various malignancies, which are also associated with high tumor grade in cervical, colon, and renal carcinomas 32-34." (PMID 36605491, 2023). "To validate the robustness of CDK1 expression in kidney papillary carcinoma, we performed multivariate survival analysis for OS using the somatic mutation data of 278 renal cancer patients including CDK1 expression and the mutations of the top five mutated genes." (PMID 33723286, 2021). "Taken together, these data demonstrated that HNRNPD exhibited an anti-tumour role in human renal cancer by modulating the ratio of the linear splicing to the backsplicing of key genes, including CDK1." (PMID 39180763, 2024). "To further explore the involvement of mTOR signaling in CDK1-dependent translational control, we analyzed MEFs overexpressing either WT mTOR or hyperactive mTOR mutants derived from renal cancer." (PMID 32040547, 2020). "The expression of CDK1 and related genes could efficiency be used as part of a prognostication scoring system in combination with other genes for renal cancer." (PMID 37047552, 2023). "Furthermore, the let-7 family targets cell cycle control proteins such as CDK1, CDK 2, CDK6 and cyclin B1 in various tumours including renal cancer cells." (PMID 36076967, 2022).
breast tumor (10 papers, 2009 to 2023). "Next, we analyzed YOD1 and CDK1 expressions by Western Blotting in the tumor tissues and found that CDK1 expression was downregulated in the tumor tissues of breast tumor-bearing mice with YOD1 knockdown." (PMID 37667382, 2023). "In consistent with the fact that circPGR regulates the expression of CDK1, CDK6 and CHEK2, the expression of these genes was significantly higher in ER-positive breast tumor tissues compared to that of adjacent normal tissues." (PMID 33408778, 2021). "We next measured the specific activities of CDK1 and CDK2 in breast tumors resected from mice 24 hours after a single dose of paclitaxel." (PMID 19239702, 2009). "The CDK1 degradation observed in both MCF7 and MCF10A cell lines when the cells were treated with DNA-damaging agents agrees with the efficacy of chemotherapy treatments for breast tumors." (PMID 28855742, 2017). "It is likely that c-myc-overexpressing breast tumors might not be sensitive to the CDK4/6 inhibition but may be more responsive to the CDK1/2 inhibitors." (PMID 32934206, 2020). "In addition, in breast tumors from patients, we found a negative correlation between CDK1 accumulation and βTrCP levels, and a positive correlation with the degree of tumor malignancy." (PMID 28855742, 2017). "Therefore, specific targeting of CDK1 might be effective for breast tumours dependent on MYC activation and this synthetic lethal strategy may overcome some problems with side effects induced by CDK1 inhibition." (PMID 24444383, 2014).
head and neck cancer (10 papers, 2012 to 2025). A primary or metastatic malignant neoplasm affecting the head and neck. "MYC along with its co-amplified partner, CDK1 are reported to be correlated with survival and prognosis in head and neck cancers." (PMID 26808319, 2016). "Accordingly, we found that the expression of both Cdk1 and Cdk2 was inhibited by esomeprazole in HN30 head and neck cancer cells." (PMID 34262645, 2021). "The strong HPV dependent activity of roscovitine cannot be attributed to the inhibition of CDK1/2, since the sensitivity of head and neck cancer cells to selective CDK1/2 inhibitor was not dependent on HPV status." (PMID 27233076, 2016). "To begin determining whether HPV+ head and neck cancer cells are sensitive to roscovitine due to specific CDK inhibition, we assessed the response of HPV-positive and HPV-negative cells to another broad CDK inhibitor, flavopiridol, as well as to specific CDK1/2 and CDK4/6 inhibitors." (PMID 27233076, 2016).
hepatoblastoma (10 papers, 2014 to 2026). Hepatoblastoma (HB) is a malignant hepatic tumor and is the most common pediatric liver cancer. "Mechanistically, ganetespib downregulated the expression of the HSP90 client protein cyclin-dependent kinase 1, a key cell cycle regulator controlling G2/M phase transition, which is heavily upregulated in hepatoblastoma." (PMID 40282517, 2025). "In hepatoblastoma, CCNA2, CDK1, and CDC20 were identified as potential therapeutic targets, with their knockdown inhibiting aggressive cell behaviors." (PMID 41511815, 2026). "CDK1 and CCNA2 have excellent performance in AUC value, sensitivity and specificity and have been identified as biomarkers in hepatoblastoma, so their functions and roles have been relatively clear." (PMID 40231267, 2025). "Increased co-expression of CCNA2 and CDK1 has been observed in hepatoblastoma, and inhibiting the expression of CCNA2 and CDK1 attenuates the proliferative, migrative, and invasive capacities of both HepG2 and HuH-6 cells." (PMID 35681641, 2022).
lymph node metastasis (9 papers, 2015 to 2026). "Co‐expression of p‐TFCP2L1 and CDK1 was an independent prognostic factor (P = 0.010) of cancer‐specific survival in multivariate analysis, in addition to age, lymph node metastasis, and muscularis propria invasion." (PMID 31709755, 2020). "Our findings showed that CDK1 protein was over-expressed in postoperative recurrence cases or in those with lymph node metastasis." (PMID 25129248, 2015). "The CDK1 protein was over-expressed in recurrent tumors or in those with lymph node metastasis." (PMID 25129248, 2015). "The evaluation included variables such as age, gender, tumor location, TNM stage, T stage, lymph node metastasis, VALSG stage, and expression levels of TOP2A and CDK1." (PMID 40765849, 2025). "Further TCGA analysis showed that miR-490-3p expression level was lower and CDK1 expression level was higher in every disease stage and in patients with or without lymph node metastasis." (PMID 33898511, 2021). "According to lymph node involvement, we have revealed lower CDK1 protein expression in patients without lymph node metastases (CDK1IRS N = 107) compared to the patients with lymph node involvement (CDK1IRS N (+) = 115)." (PMID 26912061, 2016).
retinoblastoma (9 papers, 2014 to 2025). A malignant tumor that originates in the nuclear layer of the retina. "In this study, we evaluated TOP2A and CDK1—two most differentially expressed genes within the retinoblastoma pathway that also demonstrated high predictive accuracy in machine learning-based classification— as potential biomarkers using immunohistochemistry." (PMID 41162745, 2025). "Bioinformatics analysis of multi-omics data also identified TTK, RRM2, and CDK1 as potential retinoblastoma molecular biomarkers." (PMID 38012786, 2023). "In both retinoblastoma cell lines, the levels of Bcl-2, CDK1 and PCNA were significantly upregulated in the PAX6 inhibition study groups than in negative GFP-control groups (Bcl-2, t=−5.90, P<0.05 and t=−4.86, P<0.05, resp." (PMID 24939714, 2014). "Stress response proteins that were identified to be hyperphosphorylated in retinoblastoma compared to control retina tissues included H2AFX, SIRT1, TNIK, WRNIP1, BAZ1B, and CDK1." (PMID 29914080, 2018). "We found CDK1 and CDK11 cyclin-dependent kinases to be hyperphosphorylated in retinoblastoma, indicating their activation." (PMID 29914080, 2018). "Apart from cellular stress response proteins, cell cycle proteins such as CDK1, CDK11, MCM2, MCM3, MCM5, and CCNB1 were also found to be hyperphosphorylated in retinoblastoma, implicating accelerated cell cycle progression." (PMID 29914080, 2018).